CSPG4 (chondroitin sulfate proteoglycan 4)
Diseases named in the same sentence as CSPG4 in open-access papers (continued):
Sharing a sentence is not in itself a finding about the gene and the disease.
melanoma (continued). "Another potential target is chondroitin sulfate proteoglycan 4 (CSPG4), also known as melanoma chondroitin sulfate proteoglycan (MSCP), which is expressed in 90% of melanomas as well as in sarcomas and gliomas but rarely expressed in healthy tissues." (PMID 38732242, 2024). "highlighted that chondroitin sulfate proteoglycan 4 (CSPG4)-specific CAR NKT cells, designed for melanoma, maintained the ability to eliminate target cells through their endogenous TCRs, a mechanism independent from CAR-induced activity." (PMID 38665921, 2024). "To confirm in vivo the strong antimelanoma activity mediated by CSPG4-CAR.CIK in vitro, we tested their antitumor potential in a xenograft murine model of melanoma, generated by subcutaneous grafting of M017 cells in NSG mice." (PMID 37993874, 2023). "Chondroitin sulfate proteoglycan 4 (CSPG4/NG2) was used as a targeting agent as it is highly expressed in triple-negative breast cancer (TNBC) and malignant melanoma." (PMID 36977072, 2023). "Given these encouraging preclinical reports on CSPG4 as an immunotherapeutic target, we set out to further characterize the two previously identified HLA-C*07:01-restricted melanoma reactive T-cell clones 11C/73 and 2C/165 directed against the TAA CSPG4." (PMID 37849763, 2023). "We investigated the preclinical antitumor activity of CSPG4-CAR.CIK in vitro and in a xenograft murine model focusing on patient-derived melanoma cell lines (Mel) with defective expression of HLA-I molecules." (PMID 37993874, 2023). "CSPG4-specific mouse monoclonal antibody 225.28, an IgG2a, was biotinylated and mixed with Streptavidin-ZAP, then photochemically delivered to TNBC and melanoma cells." (PMID 36977072, 2023). "In order to study the cytolytic potential of CSPG4-CAR_CD20-CCR T cells in vivo with solid tumors, a melanoma xenograft model was established with CD20+ Mel526 tumor cells." (PMID 37901209, 2023). "Photothermal ablation of the tumor combined with chondroitin sulfate proteoglycan-4 (CSPG4)-specific CAR T cells, demonstrated superior antitumor activity on melanoma WM115 cell line." (PMID 36717905, 2023). "As for human melanoma patients, CSPG4 overexpression in canine OMM is clinically relevant, since CSPG4+ OMM-affected dogs have worse prognosis than those whose tumors do not express the antigen." (PMID 35224082, 2022). "Over the past years, CSPG4-CAR-T cells generated via mRNA-electroporation were well characterized by us and others as a therapeutic option to treat melanoma." (PMID 36291817, 2022). "In the human melanoma cell lines, expression of CSPG4 (chondroitin sulfate proteoglycan 4, also known as melanoma specific proteoglycan) increased following silencing of ARSB." (PMID 36361933, 2022). "The combined effects of decline of ARSB and increase of C4S, CSPG4, and MMP2 significantly increased the invasiveness of the melanoma cells." (PMID 36361933, 2022). "CSPG4 and MC1R are surface antigens often expressed on melanoma cells, and they participate in many biological behaviors of melanoma." (PMID 35401191, 2022). "During the past decade, multiple other studies investigated the potential of CSPG4 for CTC capture and/or identification in melanoma." (PMID 32984308, 2020). "The chondroitin sulfate proteoglycan 4 (CSPG4) is a highly specific marker of the nevomelanocyte lineage and has been utilized to target melanoma." (PMID 33050185, 2020). "We investigated the anti-tumor activity and safety of the anti-CSPG4-(PDD) ADC in vitro and in human melanoma xenografts." (PMID 32331483, 2020). "Recently, however, the anti-CSPG4 mAb was used for the separation of MTEX and sEV produced by normal tissue from the plasma of melanoma patients." (PMID 32709086, 2020). "These analyses revealed fewer cells in both melanoma cell lines compared to PBS controls, and more cells in the CSPG4-low WM-1361 cells (~17% compared to PBS) compared to the CSPG4-high A375 cells (~5% compared to PBS) 4 days after ADC treatment." (PMID 32331483, 2020).
melanoma (continued). "These revealed significantly reduced colony formation in both melanoma cell lines compared to PBS controls; CSPG4-high A375 cells ~41% colony size compared to PBS, CSPG4-low WM-1361 cells ~46% colony size compared to PBS, both 7 days after ADC treatment." (PMID 32331483, 2020). "Apart from general safety issues arising from potential on-target/off tumor toxicities which are elaborated on in the melanoma section, GBM poses some distinct challenges to CSPG4-CAR-T-cell therapy." (PMID 31779130, 2019). "These markers include the two most commonly used melanoma surface markers for CTC enrichment, CSPG4 and MCAM." (PMID 31671846, 2019). "We were able to repeatedly produce a sufficient number of highly pure CSPG4-CAR-transfected T cells with a very high transfection efficiency, a high CAR expression, and a high potency to kill melanoma target cells." (PMID 31426437, 2019). "Flow cytometry analysis (FACS) revealed the presence of CSPG4 on all GBM, breast cancer, and melanoma cell lines tested, albeit at varying levels." (PMID 30625226, 2019). "In this study, we intended to exploit this disturbance in gene expression to screen for the presence of CSPG4, which is a well-established CAR-target antigen in melanoma and other solid tumors." (PMID 31195686, 2019). "T cells, virally transduced with a CSPG4-specific CAR, exerted potent cytotoxicity in response to various CSPG4-expressing tumors, such as melanoma, breast cancer, mesothelioma, glioblastoma and osteosarcoma in animal models or in vitro." (PMID 31426437, 2019). "By combining CSPG4 targeting ITs with ABT-737, targeting Bcl-2 family members, we were able to overcome widespread, inherent IT resistance in a panel of GBM, melanoma, and breast cancer cell lines." (PMID 30625226, 2019). "In human melanomas, NG2/CSPG4 functions to activate the MEK/ERK1/2 pathway by mediating the growth factor-induced activation of receptor tyrosine kinases." (PMID 29196603, 2018). "A combination of BRAFi/MEKi treatment with CSPG4-specific CAR-T-cell therapy would be a new and probably more efficient approach for melanoma therapy." (PMID 29346301, 2018). "Treatment of melanoma, TNBC and mesothelioma with mAb 9.2.27, mAb 225.28 and TP41.2, respectively, has been shown to suppress CSPG4-mediated cancer progression." (PMID 28657611, 2017). "CSPG4 was first characterized on human melanoma cells more than 30 years ago; in the same period, other studies have identified the nerve/glial antigen 2 (NG2) that is the rat orthologue of CSPG4." (PMID 28668095, 2017). "The anti-CSPG4 mAb 225.28 combined with a BRAF inhibitor exhibited synergistic antitumor effects and enhanced efficacy against BRAFV600E mutant melanoma cells in vitro compared to either agent alone." (PMID 29375561, 2017). "The combined effects of decline in ARSB on the increased expression of CSPG4 proteoglycan and of pro-MMP2 contribute to the increased invasiveness of melanoma cells." (PMID 27926479, 2017). "One of the first studies investigating the potential of anti-CSPG4 CAR T cells showed in vitro cytolytic potency against a variety of solid tumor cell lines including breast cancer, melanoma, mesothelioma, glioblastoma and osteosarcoma." (PMID 29375561, 2017). "A humanised bi-specific BiTE antibody (bi-specific T-cell engaging), able to bind both CSPG4 and human CD3 to engage the T cell receptor (TCR) complex, was designed to redirect CD3+ T cells (especially CTL) against melanoma cells." (PMID 24969320, 2014). "The chondroitin sulfate chains of CSPG4 have been shown to bind both pro-MMP-2 and MT3-MMP, an MT-MMP that is expressed on vertical growth phase melanoma and is important for melanoma invasion into collagen gels." (PMID 24069584, 2013). "They showed that PAX3 promoted a less differentiated, stem-like (via HES1, SOX9, NES, DCT), motile (via MCAM, CSPG4, and CXCR4) phenotype, characteristic of melanomas with high metastatic potential." (PMID 24069584, 2013).
melanoma (continued). "This review has focused on five molecules involved in melanoma metastasis – MCAM, Gal-3, CSPG4, MMP-2, and PAX-3." (PMID 24069584, 2013). "This antigen can distinguish metastatic melanoma cells in sentinel lymph nodes by immunohistochemistry and qRT-PCR assays, and CSPG4 is more sensitive and more specific than MART-1, a commonly used melanoma marker." (PMID 24069584, 2013). "We hypothesize that the physical interaction between the CSPG4-scFv and CSPG4 on the surface of melanoma cells is sufficient to promote CAR-M-mediated engulfment of melanoma fragments, likely via the maintenance of endogenous FcRγ signaling." (PMID 40082557, 2025). "CSPG4 has also been shown to be expressed at the mRNA level in a primary melanocytic cell line (HEM1455), established from human neonatal foreskin, but at lower levels compared with a metastatic melanoma cell line (A2058)." (PMID 40700516, 2025). "CSPG4 is frequently highly expressed in melanoma tumors, and expression in non-malignant cells is low, making it an ideal target antigen." (PMID 40082557, 2025). "When CSPG4-targeting CAR-Ms are combined with CD47 blocking antibodies, thereby blocking a key tumor cell “don’t eat me” signal, we observe enhanced phagocytosis of melanoma cells and robust inhibition of melanoma spheroid growth in 3D." (PMID 40082557, 2025). "Notably, we identified differentially expressed cell surface markers including MCAM (CD146), CSPG4, and ITGA6/ITGA7, which are well-established melanoma resistance markers." (PMID 41000875, 2025). "We demonstrate that in a xenograft model, with mice lacking adaptive immune cells, CSPG4-targeting CAR-Ms exhibit sustained inhibition of melanoma growth." (PMID 40082557, 2025). "Thus, given the high expression of CSPG4 on melanoma cells, we sought to use this established tumor antigen to test whether engineering macrophages to target an antigen on melanoma cells will lead to high macrophage infiltration into melanoma tumors and robust melanoma phagocytosis and clearance." (PMID 40082557, 2025). "None of the antibodies bound to hHER2-negative A2058 melanoma cells, while an IgE specific for the melanoma antigen chondroitin sulfate proteoglycan 4 (CSPG4) was shown to bind to these CSPG4-expressing cells." (PMID 39934835, 2025). "These vaccine targets are non-mutated melanoma-associated antigens that show high and prevalent expression in melanoma, restricted expression and distribution in non-malignant tissues, and immunogenicity, characteristics that are shared with CSPG4." (PMID 39409881, 2024). "Induction of CSPG4 expression in a CSPG4-negative human melanoma cell line enhanced integrin-mediated cell spreading as well as activation of FAK and MAPK/ERK pathways, both associated with malignant progression in melanoma." (PMID 39409881, 2024). "The anti-CSPG4 IgG1 constructs demonstrated the ability to mediate substantially effective antibody-dependent cellular phagocytosis (ADCP) in patient-derived monocytes and reduced tumour size in human melanoma xenograft models." (PMID 39409881, 2024). "Since these melanoma cells do not express CSPG4, a suspected mechanism of action of this DNA vaccination was through triggering an immune response targeting the CSPG4-expressing pericytes in tumour blood vessels." (PMID 39409881, 2024). "For example, a CSPG4-specific IgG2 mAb clone conjugated to doxorubicin (DXR) via an acid-sensitive linker enhanced tumour-killing cytotoxicity in vitro and suppressed tumour growth in human melanoma-bearing immunodeficient (nude) mice." (PMID 39409881, 2024). "Obstacles preventing that progress include limited knowledge of CSPG4 function in human cancer and a lack of in vivo models that adequately represent patient immune responses and human melanoma biology." (PMID 39409881, 2024).
melanoma (continued). "Chondroitin sulfate proteoglycan 4 (CSPG4) is a cell surface molecule overexpressed in human melanoma, with restricted distribution and low expression in non-malignant tissues and involved in several cancer-promoting and dissemination pathways." (PMID 39409881, 2024). "Melanoma xenograft weights (29 days after tumor challenge) were significantly lower in mice given intravenous treatment with CSPG4 IgE compared with no antibody or non-specific isotype IgE control groups (left)." (PMID 37185332, 2023). "Contrastingly, CSPG4 IgE-engaged effector cells did not trigger ADCC of intermediate CSPG4-expressing WM1366 melanoma cells, or of non-expressing primary human melanocytes (respectively)." (PMID 37185332, 2023). "Additionally, boosting through cis activation allows the targeting of tumor-initiating CD20+ CSPG4+ melanoma cancer stem cells, which is supported by the clinical success using the anti-CD20 antibody Rituximab for treatment of melanoma." (PMID 37901209, 2023). "CSPG4 (Chondroitin Sulfate Proteoglycan 4), also known as NG2 or MCSP, is a transmembrane proteoglycan that is found on the outer layers of various cell types, including pericytes, glial cells, and melanoma cells." (PMID 37858084, 2023). "The antimelanoma activity of CSPG4-CAR.CIK was intense regardless of HLA-I expression level on melanoma cells, including a patient-derived melanoma cell line lacking HLA-I surface expression due to a mutation in the β2m gene." (PMID 37993874, 2023). "CSPG4 IgE triggered significantly greater degranulation than the non-specific isotype control, NIP IgE, in the presence of high CSPG4-expressing A375 and A2058 melanoma cells." (PMID 37185332, 2023). "CAR-NKT cells targeting chondroitin sulfate proteoglycan-4 (CSPG4), CD38, and the plasma cell-specific B cell maturation antigen (BCMA) have also been developed and showed CAR-specific as well as TCR-dependent cytotoxicity against melanoma cells." (PMID 37147740, 2023). "CSPG4 has been previously investigated as an immunotherapeutic target for CAR T cells, among others in melanoma and glioblastoma, and we also observed specific recognition in a panel of CSPG4+/HLA-C*07:01+ melanoma and glioblastoma cell lines." (PMID 37849763, 2023). "Melanoma antigens found in EVs are Melan-A/MART-1, glycoprotein 100 (gp100), tyrosinase-related protein (TYRP), melanoma antigen gene family (MAGE), very late antigen 4 (VLA-4) and CSPG4." (PMID 37022605, 2023). "We investigated whether, in addition to the direct tumor killing activity, CSPG4-CAR.CIK could also modulate and favor HLA-I expression on melanoma cells." (PMID 37993874, 2023). "Neither CSGP4 IgE, nor a non-CSPG4 control IgE, triggered basophil activation when incubated ex vivo in whole blood samples from patients with melanoma (n = 15)." (PMID 37185332, 2023). "Compared to non-specific IgE, CSPG4 IgE significantly decreased subcutaneous melanoma tumor volume and weight, and lung lesional growth, in healthy volunteer and melanoma patient-derived immune cell-engrafted mice." (PMID 37185332, 2023). "CSPG4 IgE-mediated ADCC of A375 and A2058 melanoma cells was triggered by monocytes derived from both healthy participants (right) and patients with melanoma." (PMID 37185332, 2023). "Taken together, our data suggest that any molecules present in the melanoma patient circulation, or intermediate-low CSPG4-expressing cells, did not have the capacity to activate basophils." (PMID 37185332, 2023). "Ex vivo stimulation of whole unfractionated blood samples from melanoma patients with CSPG4 IgE did not induce basophil activation, despite clear activation by well-described IgE and non-IgE specific immune stimuli in the same samples." (PMID 37185332, 2023). "CSPG4 is highly expressed in various refractory malignant tumors, such as triple-negative breast cancer, glioblastoma, mesothelioma, and melanoma." (PMID 35401191, 2022).
melanoma (continued). "A study reported that CSPG4 is overexpressed in more than 90% of melanoma lesions and is not present in healthy adult tissues." (PMID 35401191, 2022). "Notably, human melanoma cells expressing CSPG4 also exhibit constitutive activation of ERK1/2, a process that requires the presence of intact CSPG4 core protein and cytoplasmic domain." (PMID 36428658, 2022). "A study showed that anti-CSPG4 NKT cells could be transiently transfected using electroporation, with improved activity, and the in-vitro functionality after stimulation with melanoma cells was assessed." (PMID 34207884, 2021). "Compared to conventional CAR T cells, the anti-CSPG4 NKT cells generated a lower amount of cytokines, such as IFN-γ and TNF, but could still effectively kill melanoma cells." (PMID 34207884, 2021). "This conclusion is supported by the following additional lines of evidence: no toxicity was detected in melanoma patients who developed CSPG4-specific antibodies after immunization with anti-idiotypic antibodies which mimic CSPG4." (PMID 34113233, 2021). "In another study anti-CSPG4 CAR T cells transfected with siPD-1 and siCTLA4 showed reduced expression of PD-1, and were able to secrete higher quantities of cytokines and a good cytolytic effect against the A375M melanoma cell line." (PMID 34207884, 2021). "As expected, neither the anti-CSPG4 antibody nor isotype-(PDD) ADC had any effects on cell viability in any of the three melanoma cell lines." (PMID 32331483, 2020). "Using antibodies against chondroitin sulfate proteoglycan 4 (CSPG4), a tumor antigen selectively expressed by melanoma and other malignant but not normal cells, melanoma-derived TEX were successfully isolated from patients’ plasma." (PMID 32517240, 2020). "Linked by a network of overlapping functions in melanoma progression, melanoma cell adhesion molecule (MCAM), galectin-3 (Gal-3), chondroitin sulfate proteoglycan 4 (CSPG4), matrix metalloproteinase 2 (MMP-2), and paired box 3 (PAX-3) potentially act as biomarkers and targets in melanoma metastasis." (PMID 33490091, 2020). "Apart from compromising the targetability of melanoma cells by antigen-shedding, soluble CSPG4 might act as a decoy through blocking the CSPG4-binding site of circulating CSPG4-CAR-T cells, which could prevent the recognition of bona fide melanoma cells." (PMID 31779130, 2019). "Of note, the challenge to deal with potential of on-target/off-tumor toxicity is not confined to melanoma but bears relevance for CSPG4-CAR-T-cell therapy in general, irrespective of the cancer entity." (PMID 31779130, 2019). "Despite abundant CSPG4 cell surface expression, in vitro cytotoxicity assays demonstrated that all GBM xenografts, all breast cancer cell lines, and the DM443 melanoma cell line were highly resistant to both Mel-14-PE38KDEL and 9.2.27-PE38KDEL ITs (IC50 >100 ng/ml)." (PMID 30625226, 2019). "Collectively, targeting melanoma with CSPG4-CAR-T cells in conjunction with BRAFi/MEKi might reveal synergistic effects on tumor regression and reduce the frequency of CSPG4 down-regulation by simultaneously engaging two important oncogenic drivers." (PMID 31779130, 2019). "To test this hypothesis, we used the melanocyte-derived radial growth phase melanoma cell line WM-1552, which was transfected to stably express CSPG4 and was designated as WM1552-CSPG4." (PMID 30333973, 2018). "Importantly, SynCon® CSPG4 significantly slowed tumor growth and increased survival in the YUMM1.7 mouse model of melanoma." (PMID 30400835, 2018). "In the current study, we compared TNT formation in WM1552c mock transfectants lacking CSPG4 with WM1552c CSPG4-expressing melanoma cell lines." (PMID 30333973, 2018). "First evidences of the effectiveness of active immunization against CSPG4 in melanoma patients were achieved through vaccination with the anti-idiotypic antibody MK2-23, which bears the internal image of the mAb 763.74 against a defined CSPG4 epitope." (PMID 28668095, 2017).